SRC (SRC proto-oncogene, non-receptor tyrosine kinase)
Diseases named in the same sentence as SRC in open-access papers (continued):
Sharing a sentence is not in itself a finding about the gene and the disease.
cancer (continued). "Similarly in PDAC cancer cells, S63845 also significantly modulated the expression of Cofilin and the Y416 phosphorylated and activated form of SRC." (PMID 31735913, 2020). "In cancer cells, aberrant HGF/c-Met axis triggering, which is strongly linked to c-Met gene mutations and amplification, promotes tumor development/progression by inducing the PI3K/AKT, Ras/MAPK, JAK/STAT, SRC, Wnt/β-catenin, and other signaling pathways." (PMID 33226369, 2020). "SRC was among the first oncogenes to be discovered and encodes a non-receptor protein tyrosine kinase that regulates many cancer-related cellular processes including mitogenesis, angiogenesis, adhesion, invasion, migration, and survival." (PMID 32509799, 2020). "Although genetic mutations in SRC gene are not driver events in tumorigenesis, several studies documented its de-regulation in diverse cancer types, inducing alteration of many signaling pathways." (PMID 32517369, 2020). "Hence, targeting SRC has emerged as a promising therapeutic strategy for cancer treatment, and a number of SRC inhibitors have subsequently been developed and tested." (PMID 31731442, 2019). "Our findings suggest that this elevated SRC activity may be one important driver of the aberrantly high YAP/TAZ activity observed in many human cancers." (PMID 30559289, 2019). "This reveals SRC as a potential therapeutic target for the treatment of YAP/TAZ-driven cancers." (PMID 30559289, 2019). "This makes therapies that target SRC a potential treatment for YAP/TAZ-dependent cancers." (PMID 30559289, 2019). "The SFK function in cancer cells is independent of its mutation status, c‐SRC activation by oncogenic mutations has not been detected in most cancers." (PMID 29318780, 2018). "In cancer cells, SRC, ERK and JNK activation would mediate the VE-cadherin/integrin signalling." (PMID 27966446, 2017). "EGFR and SRC have been reported to functionally synergize to form more aggressive cancers." (PMID 28513565, 2017). "AZD0530, an SRC inhibitor, has been reported to exhibit clinical activity in cancer patients." (PMID 28396832, 2017). "Quite interestingly, genes and associated interaction partners that were downregulated upon Hic-5 KD comprised members and/or associated partners of the TGFβ pathway (including TGF-β2, TGFβR, TGFβRII, FGF2, CTGF, FGFR, SRC, RUNX2 and CDH2), that are commonly implicated in inducing EMT in cancer." (PMID 29137281, 2017). "Furthermore, genes reported to promote tumor metastasis in various cancers, including SRC, TGFB1 and MMP9, were upregulated by CTCF." (PMID 28977939, 2017). "The relevance of this finding is further supported by recent unfortunate observations, revealing that although SRC is frequently overexpressed in cancer, in some clinical trials randomly applied SRC inhibition produced limited positive effects on cancer patients." (PMID 27418135, 2016). "Crosstalk between AR and SRC has been observed in human cancer." (PMID 27028864, 2016). "The SRC proto-oncogene is commonly overexpressed or activated during cancer development." (PMID 27526105, 2016). "Aberrant SRC activity is observed in several human cancers, including GC, and it may be important during tumor development and progression." (PMID 26460485, 2015). "We found that fibroblasts induce cancer cell motility and invasion in a cell-contact dependent manner and we provide a mechanism: Fibroblasts surface associated FGF-2 activates FGFR on cancer cells, which in turn activates SRC." (PMID 25973543, 2015). "Aberrant SRC activity has already been observed in several human cancers, including GC." (PMID 26460485, 2015). "Consequently, SRC functions as an oncogene to favor proliferation, migration, and invasion of various types of cancer cells." (PMID 25140799, 2014).
cancer (continued). "The c-SRC non-receptor tyrosine kinase is overexpressed and activated in a large number of human malignancies and has been linked to the development of cancer and progression to distant metastases." (PMID 24709904, 2014). "SRC contributes to cancer progression by triggering cell proliferation, migration, and invasion." (PMID 25301722, 2014). "c-SRC has been reported to increase STAT3 activity in carcinoma cells including MC." (PMID 25266665, 2014). "Dasatinib is a clinically studied SRC inhibitor for cancer therapy." (PMID 23590835, 2013). "SRC encodes a nonreceptor tyrosine kinase that in its active form contributes to many hallmarks of cancer including cell proliferation, migration, and angiogenesis." (PMID 22482061, 2012). "Additionally, SRC has been reported to play a crucial role in tumor progression and mediate cancer development and metastasis." (PMID 22383989, 2012). "For instance, in the ‘gene expression, cancer and cell morphology’ network, miR-218 may target genes directly and indirectly linked to two oncogenes, MYC and SRC." (PMID 20838434, 2010). "Pathways such as MYC and SRC represent one opportunity but the concept can go well beyond to include other, less defined, cancer relevant phenotypes that can be represented as expression signatures including poor prognosis, metastasis, or general resistance to therapies." (PMID 19714244, 2009). "However, SRC oncogenic mutations are rarely detected in human cancer, suggesting the existence of important non-genetic mechanisms driving Src kinase overactivation and cell transformation." (PMID 40081987, 2025). "We found that higher SRC expression is significantly associated with activated RTK (receptor tyrosine kinase; 16%) and TSC/mTOR (tuberous sclerosis complex/mechanistic target of rapamycin; 12%) pathways in pan-cancer, indicating its potential role in promoting cell growth and survival." (PMID 39859167, 2025). "In vitro studies, such as treating cancer cell lines with small-molecule inhibitors (e.g., SRC inhibitors like dasatinib or trametinib) or inducing mitophagy via PINK1 activators, could further elucidate the therapeutic relevance of these genes in overcoming drug resistance." (PMID 39859167, 2025). "SRC is a non-receptor tyrosine protein kinase encoded by a specific proto-oncogene, which plays a pivotal role in the growth, progression, and metastasis of cancer." (PMID 39205203, 2024). "Consequently, ICAM1 may potentiate SRC signaling, thereby promoting the malignant potential of cancer." (PMID 38907234, 2024). "Interestingly, cancer cells with higher SRC expression were more resistant to VU‐0365114." (PMID 37842807, 2024). "Our work implies that GSTP1 plays a dominant role linking G6PD and SRC to form a “signalosome” that provides a basis, under metabolic stresses, for robust cancer cell proliferation upon lactic acid signaling, which could regulate many aspects of cellular metabolism." (PMID 37491277, 2023). "Indeed, SRC(Y527) and RAF are associated with cell proliferation pathways, and STS samples had higher median levels of these proteins, indicating their contribution to cancer tissue growth." (PMID 37237151, 2023). "Moreover, emerging preclinical evidence has demonstrated that TNBC cells showed higher sensitivity to the c-SRC inhibitor than do other cancer subgroups by targeting BCSCs, further highlighting the potential significance of targeting BCSCs through inhibiting SRC activity in TNBC treatment." (PMID 36633714, 2023). "Indeed, the crucial role of SRC in many aspects of tumor development including migration, invasion and survival has warranted the use of SRC inhibitors to disrupt these effects in several cancer types." (PMID 36305167, 2022). "We sought to characterise how AZD0424, and by extension SRC inhibitors in general, may be employed as part of anti‐cancer combination therapy in CRC as AZD0424 treatment could repress transducers of downstream signalling from EGFR, a key driver of metastatic CRC." (PMID 34856074, 2022).
cancer (continued). "Moreover, ROR1 interacts with SRC, a key regulator of cancer cells." (PMID 36297673, 2022). "Consequently, ICAM-1 may further accelerate SRC signaling, promoting the malignant potential of cancer." (PMID 35487888, 2022). "Interestingly, preclinical and clinical evidence demonstrated that BCR-ABL/SRC inhibitors enhance the cytotoxic effects of T-cells and the efficacy of ICBs, suggesting that BCR-ABL/SRC inhibitors not only target the cancer cells but also modulate the tumor immune microenvironment." (PMID 33805359, 2021). "Hypothesizing that the purely cytostatic response observed with SRC inhibition alone necessitates co-targeting of bypass signaling pathways, we performed a combination drug screen to identify drugs that synergized with dasatinib to kill cancer cells." (PMID 34095877, 2021). "However, this cell line could be useful to provide additional insights into the therapeutic values of HER2/SRC inhibition in fusion positive cancer cells." (PMID 32771039, 2020). "Moreover, high SRC activity has also been reported in a panel of GBM cancer cell lines." (PMID 32545574, 2020). "Interestingly, hyperactivation of SRC could occur both in cancer cells and in immune inflammatory cells due to the inflammatory cytokines released in the TME." (PMID 32545574, 2020). "Our findings suggest that therapies targeting SRC could help manage some YAP/TAZ-dependent cancers." (PMID 30559289, 2019). "This suggests that SRC is not the only cause of YAP/TAZ activation in cancer." (PMID 30559289, 2019). "Notably, Food and Drug Administration–approved therapies that target SRC already exist and could potentially be repurposed for use in cancers in which SRC is driving YAP/TAZ activation." (PMID 30559289, 2019). "Indeed, changes in growth factor signaling, cell–cell adhesion, G-protein–coupled receptor signaling, metabolic cues, and cell polarity cues have each been shown to increase SRC activity in cancer cells (76, –, 79, 82), and each of these can also increase YAP/TAZ activity." (PMID 30559289, 2019). "Furthermore, SRC inhibition by AZD0530 was effective in ALK‐resistant cancer cells." (PMID 28396832, 2017). "Furthermore, EC-70124 inhibited SRC and reduced migration of cancer cells." (PMID 26418718, 2015). "Furthermore, pro-oncogenic properties make c-SRC an important target in cancer research." (PMID 26696895, 2015). "Even though FGR has not been genetically linked to cancer to date, it has been hypothesized that its expression could compensate for SRC inhibition." (PMID 25204415, 2014). "Additionally, we examined whether SRC protein overexpression was also observed in other human cancers." (PMID 24130815, 2013). "Network analysis highlighted STAT3, EGFR, SRC, IL-6, and AKT1 as key hub targets, with enrichment in cancer-related, EGFR resistance, and PI3K-Akt pathways." (PMID 42123459, 2026). "Network toxicology indicated that AEF modulates targets such as SRC, AKT, and HSP90AA1, thereby influencing pathways including the PI3K-AKT signaling pathway and pathways in cancer." (PMID 42043040, 2026). "In the PC vs para-PC network, key hub proteins, such as SRC, PTEN, and HDAC1—known regulators of cancer signaling and epigenetic control—were prominent." (PMID 40358702, 2025). "Here, we illustrate that SRC modulates autophagy through BECN1 phosphorylation, which plays an essential role in aberrant cell proliferation in multiple cancer types." (PMID 40754831, 2025). "Elevated expression of proteins and phosphoproteins of downstream of EGFR/ERBB in cluster #3 and #1 suggests EGFR/ERBB, SRC, c-RAF/MAPK, and PI3K/AKT/mTOR/RICTOR signaling as a major tumor-promoting circuits of these cancers." (PMID 40011822, 2025). "The high degree of interaction observed in genes like MAPK3, MAP3K1, SRC, and RAF1 further supports their roles in regulating cellular signaling, which is crucial for understanding cancer biology and therapeutic resistance." (PMID 40136517, 2025).
cancer (continued). "It is important to clarify that not all of these proteins act exclusively as tumor suppressors; some, such as EGFR, STAT3, SRC, and HSP90AA1, are oncogenic drivers whose inhibition can suppress cancer growth." (PMID 41150809, 2025). "SRC and FAK have had their moments too, with CL1‐YL2 making headway against SRC signaling and FAK degraders showing promise for blocking cancer cell migration." (PMID 41049269, 2025). "Last, we gathered the IC50s of a wide variety of drugs among different cancer cell lines through the GDSC and CTRP databases and assessed the relationship between the mRNA values of MAP1LC3A, OPTN, SRC, BNIP3L, BECN1, PINK1, and PRKN and drug sensitivity." (PMID 39859167, 2025). "For instance, SRC regulates YAP, a known promoter of drug resistance and cancer progression in NSCLC." (PMID 39941857, 2025). "Overall, the Spearman’s correlation coefficients varied across different cancer types, revealing distinct patterns of immune cell correlation with the expression of OPTN, PINK1, MAP1LC3A, PRKN, BNIP3L, BECN1, and SRC." (PMID 39859167, 2025). "Critical targets such as TNF, EGFR, ESR1, HIF1A, HSP90AA1, and SRC were involved in pathways including chemical carcinogenesis, PI3K‐Akt signaling, proteoglycans in cancer, receptor activation in chemical carcinogenesis, and immunomodulation." (PMID 40144560, 2025). "We discovered that two cancer-driving proteins, ALK and SRC, directly modify and activate a key metabolic enzyme called IMPDH2." (PMID 41154443, 2025). "In conclusion, the results from this study support the therapeutic potential of dual inhibition of AXL and SRC towards KRAS mutant NSCLC therapies and will aid in our understanding of molecular mechanisms behind TKI therapies in KRAS mutant harboring cancers." (PMID 39941857, 2025). "To validate this connection, we ran a correlation analysis of SRC and FAK with CD318 in four highly CD318-expressing cancers, such as COAD, CESC, LUAD, and PAAD." (PMID 40725832, 2025). "We delved into the molecular mechanisms by which LC3, PINK1, PRKN, SRC, BNIP3L, BECN1, and OPTN regulate mitophagy, cancer progression and drug sensitivity or resistance." (PMID 39859167, 2025). "The analysis of CNVs in PRKN, OPTN, PINK1, SRC, BNIP3L, BECN1, and MAP1LC3A across various cancer types revealed significant heterogeneity in the types and frequencies of CNVs." (PMID 39859167, 2025). "While the selected genes play established roles in mitophagy, many of them, such as SRC and BECN1, are also involved in other cellular pathways, including autophagy and cancer-related signaling." (PMID 39859167, 2025). "Significant changes in mRNA expression levels were identified across eight cancer types, with PRKN and PINK1 being generally downregulated and SRC being upregulated." (PMID 39859167, 2025). "Among these shared targets, several key genes involved in cancer-related pathways were identified, including EGFR, PARP1, SRC, MET, GSK3B, and CYP19A1." (PMID 40963691, 2025). "Other KDs were associated with signal transduction and kinase activity (PRKCA, TAOK1, and ADRBK1), membrane transport (SLC9A3R1), metabolism (PPP1R3B), gene regulation (USF1), and immune responses and cancer (SLAMF8, SRC, and KIAA0100)." (PMID 41402937, 2025). "In the development and progression of cancer, AKT1, JUN, IL6, SRC, EGFR and BCL2 plays a critical role." (PMID 39011503, 2024). "Network pharmacology with the relevant databases and software was used to predict potential targets like CASP3, SRC, ESR1 and JAK2 and pathways such as PI3K-Akt, proteoglycans and focal adhesion in cancer." (PMID 38675723, 2024). "The possible molecular mechanism involved in cancer pathways, PI3K-Akt signaling pathway and viral carcinogenesis pathway via the inhibition of CASP3, MMP3, SRC, MAPK10 and CDK6 and the activation of PPARα and JAK." (PMID 38675723, 2024).
cancer (continued). "The possible molecular mechanism involves inhibiting cleaved CASP3, MMP3, SRC, MAPK10 and CDK6, and activating PPARα and JAK, which are typically involved in cancer pathways, the PI3K-Akt signaling pathway and viral carcinogenesis pathways." (PMID 38675723, 2024). "We also demonstrated that an irreversible covalent inhibitor of SRC, DGY-06-116, which targets cysteine-277 in the P-loop, enhances the antitumor activity of MRTX849 in multiple KRAS-G12C cancers." (PMID 39661665, 2024). "In cancer, hnRNPK binds to the promoter regions of MYC (MYC proto-oncogene) and SRC (SRC proto-oncogene) to elevate their transcription or binds to their mRNAs to control translation." (PMID 36735291, 2023). "Researchers have examined the effects of the combination of SRC and MEK inhibitors on other cancer types with activation of the MAPK pathway." (PMID 36952536, 2023). "We, for the first time, show that the tumor metabolic microenvironment lactic acid activates a “signalosome” comprising GSTP1, SRC and G6PD by attenuating the complex, which facilitates a reprogrammed PPP to promote cancer cell growth." (PMID 37491277, 2023). "The activation of SRC can disrupt epithelial cell-cell junctions and induce epithelial-mesenchymal transition (EMT), which contributes to tumor cell invasion and cancer progression." (PMID 37046850, 2023). "For example, it can interact with other transcription factors such as NF-Y to enhance signaling pathways like JNK/c-JUN, SRC/FAK, and SRC/ERK, thereby promoting stroma remodeling, cancer cell proliferation, and EMT." (PMID 37760801, 2023). "Meanwhile, other cancer stemness-related markers, such as OCT4, NANOG and C-MYC were also slightly induced after SRC activation." (PMID 36633714, 2023). "The transactivation process is impaired by MMP and SRC inhibitors, such as GM6001 or PP2; however, these agents inhibit signal transduction in normal cells as well as cancer cells." (PMID 37508387, 2023). "This is the first report to demonstrate the transcriptional regulation of SRC induced by an TGF-β-responsive enhancer, which helps to elucidate how SRC is overexpressed in various types of human cancer." (PMID 37439249, 2023). "Moreover, the activation of signaling pathways involved in sustaining cancer proliferation, including EGFR, HER2, B-RAF, ERK, mTOR, AKT, and SRC, have been identified in association with ADPKD, accumulating evidence that polycystins may be involved in cancer development and progression." (PMID 37510333, 2023). "For example, SRC can enhance the phosphorylation of epidermal growth factor receptor (EGFR) and promote cell transformation and cancer development." (PMID 37172717, 2023). "This set of highly variable kinases contains known cancer drivers and kinases with inhibitors already used in the clinic as cancer treatment, such as BRAF, AKT, MAP2K1, SRC among others." (PMID 36688815, 2023). "Three SRC inhibitors, KX2-391, bosutinib, and saracatinib, which had undergone clinical trials for other cancer types, were chosen for testing of their anti-tumor effects on a panel of eight NPC cell lines." (PMID 37046850, 2023). "According to bioinformatics prediction, ERBB2, SRC, TNF receptor, and AKT1 were predicted to be the key targets and play an essential role in cancer treatment." (PMID 36500678, 2022). "We show that ectopic active PTK6 enhances activating phosphorylation of SRC at Tyr416, and knockdown of endogenous PTK6 results in downregulation of SRC Tyr416 phosphorylation in different cancer cell lines." (PMID 36228719, 2022). "Here we report a central role of SRC in mediating “bypass”-resistance to MEK inhibition (MEKi), primarily in cancer stem cells (CSCs)." (PMID 35272617, 2022). "Our results suggested that Lon-induced Ca2+-dependent cisplatin resistance is involved in chemotherapy-induced cancer stemness, which is consistent with the reported roles of PYK2, SRC, and STAT3/IL-6 in the enrichment of cancer stem cells." (PMID 35296653, 2022).